IL2RA (interleukin 2 receptor subunit alpha)
Diseases named in the same sentence as IL2RA in open-access papers (continued):
Sharing a sentence is not in itself a finding about the gene and the disease.
Immunodeficiency (11 papers, 2011 to 2024). Failure of the immune system to protect the body adequately from infection, due to the absence or insufficiency of some component process or substance. "Human CD25 deficiency, caused by mutation in the IL2RA gene, is a combined immunodeficiency characterized by invasive viral and bacterial sinopulmonary infections, lymphoproliferation, and severe multi-organ autoimmune disorders." (PMID 29988287, 2018). "For example, mutations in IL2RA and IL7R cause immunodeficiency and mutation in TYK2 and STAT3 have been reported to cause hyper-IgE syndrome." (PMID 21552549, 2011).
systemic lupus erythematosus (10 papers, 2009 to 2025). An autoimmune multi-organ disease typically associated with vasculopathy and autoantibody production. "The objective was to test the genetic association of systemic lupus erythematosus (SLE) and anti-neutrophil cytoplasmic antibody (ANCA) – associated systemic vasculitis (AAV) with SNPs in the IL2RA region and to correlate genotype with serum levels of IL-2RA." (PMID 19265545, 2009). "In systemic lupus erythematosus (SLE), SNPs without any prior autoimmune associations [rs7072793, rs4147539, rs7090530 and rs12251307] were examined in a candidate gene analysis of IL2RA, providing weak evidence for association." (PMID 19265545, 2009).
autoimmune thyroid disease (8 papers, 2009 to 2025). Inflammatory disease of the thyroid gland due to autoimmune responses leading to lymphocytic infiltration of the gland. "Furthermore, IL2RA has been identified as a susceptibility gene for autoimmune thyroid disease." (PMID 38332917, 2023). "IL2RA (interleukin 2 receptor subunit alpha) and hypothyroidism: IL2RA is involved in the regulation of T-cell function and has been related to autoimmune thyroid disease (AITD)." (PMID 36782330, 2023).
colitis (8 papers, 2017 to 2025). Inflammation of the colon. "Consistent with this idea, a recent study reported that the duplication of IL2RA locus results in excessive IL-2 signaling and that this predisposed to colitis in patients with inflammatory bowel disease." (PMID 40680114, 2025). "In contrast, our results from the adoptive transfer colitis model demonstrate that efficient IL-2R signaling is important for Treg cell stability and function during inflammation, implying that IL-2Rα-independent signals cannot compensate for low IL-2R signaling under such settings." (PMID 33408345, 2021). "Interestingly, mice with genetic deletion of IL-2 receptor subunit alpha (IL2RA, CD25), a representative marker for regulatory T (Treg) cells, spontaneously develop periportal inflammation with biliary duct injury and colitis mimicking human IBD58." (PMID 37464092, 2023). "A 16-gene signature (CARD12, CCL3, CCR3, CXCL1, F5, FAM210B, GADD45A, IL18bp, IL2RA, IL5, IL8, MMP9, PTGS2, SOCS3, TLR9 and UBE2C) was identified from 30 days post-tremelimumab initiation blood that discriminated patients developing grade 0–1 from grade 2–4 diarrhea/colitis." (PMID 30227886, 2018).
ovarian carcinoma (8 papers, 1993 to 2025). A malignant neoplasm originating from the surface ovarian epithelium. "Both immunocytokines enhanced the formation of synapses between NK cells and melanoma or ovarian carcinoma, which was inhibited by an anti-IL-2 receptor α (IL-2Rα) antibody, suggesting that synapse formation was based on IL-2R engagement on NK cells by the cancer cell-bound immunocytokines." (PMID 33803078, 2021).
cervical cancer (7 papers, 2012 to 2024). A primary or metastatic malignant neoplasm involving the cervix. "Lastly, the IL2RA rs2476491 T variant was also associated with significantly decreased risk of cervical cancer (ORAT/TT=0.69, 95%CI 0.51–0.92, Ptrend=0.02)." (PMID 22496757, 2012). "The expression of FOXP3 and IL2RA, the marker genes to calculate the relative infiltration of Tregs, were both evenly expressed in healthy cervical cancer tissue and cervical cancer tissues." (PMID 35087740, 2021). "Therefore, we concluded that both genes FOXP3 (transcriptional factor) and IL2RA (cytokine) have an important function in healthy cervical tissue samples and cannot be used as accurate marker genes to identify Tregs cells in cervical cancer." (PMID 35087740, 2021).
lung carcinoma (7 papers, 1994 to 2024). "Previous studies have demonstrated that polymorphisms in the immunomodulatory gene IL2RA are linked to an increased risk of lung cancer and the development and progression of acute myeloid leukemia in the Chinese Han population." (PMID 39308669, 2024). "The experiments indicated that there is a dynamic and inverse correlation between downregulation in the levels of CDH1 (encoding the epithelial cell marker E-cadherin) and the observed increase in the IL2RA (encoding the Treg marker CD25) in stage IV lung cancer patients resistant to chemotherapy." (PMID 36776832, 2023).
schizophrenia (7 papers, 2019 to 2023). A major psychotic disorder characterized by abnormalities in the perception or expression of reality. "IL-2Rα is like the other IL-2R subunits expressed by Treg cells and recently activated T cells, and elevated plasma levels of soluble IL-2Rα indicate ongoing pro-inflammatory immune activity and are reported in mood disorders, schizophrenia, and ASD." (PMID 36904292, 2023).
acute myeloid leukemia (6 papers, 2019 to 2024). Acute myeloid leukemia (AML) is a group of neoplasms arising from precursor cells committed to the myeloid cell-line differentiation. "The IL2RA gene regulates proliferation, differentiation, apoptosis, and leukemogenesis and is associated with a variety of diseases, such as acute myeloid leukemia prognosis." (PMID 36164371, 2022). "Elevated expression of IL2RA is associated with poor prognosis and may act as a biomarker in acute myeloid leukemia." (PMID 34888353, 2021). "The gene expression for interleukin-2 receptor subunit alpha (CD25/IL2RA) is frequently altered in adults with acute myeloid leukemia (AML)." (PMID 32687530, 2020). "Elevated protein expressions of CD markers such as IL2RA/CD25, CXCR4/CD184, CD34 and CD56 are associated with adverse prognosis in acute myeloid leukemia (AML)." (PMID 31171000, 2019). "There is a close relationship between UNC93B1, IL2RA, HSPA1B, and SOCS1 overexpression and chemotherapy resistance in patients with acute myeloid leukemia (AML)." (PMID 39213256, 2024).
alopecia areata (6 papers, 2013 to 2024). Loss of scalp and body hair involving microscopically inflammatory patchy areas. "We found a significant risk effect for rs3118470 of the IL2RA gene in the dominant and homozygous models with alopecia areata." (PMID 38394507, 2024). "Our analysis showed that mutation of rs3118470 of IL2RA gene possesses a significant risk effect for alopecia areata." (PMID 38394507, 2024). "Our study showed that polymorphisms of rs3118470 of the IL2RA gene were significantly associated with alopecia areata." (PMID 38394507, 2024). "This analysis restricted jal’s position between D2Mit359 and D2Mit80, an interval that includes Il2ra (for interleukin 2 receptor, alpha chain), a gene that is known to be associated with alopecia areata in humans." (PMID 23659281, 2013). "We found a significant risk effect for rs3118470 of the IL2RA gene with alopecia areata in the dominant model (CC + CT vs TT; OR = 1.54, 95% confidence interval = 1.05–2.26, P < .05, I2 = 69.03%) and homozygous model (CC vs TT; OR = 2.00, 95% confidence interval = 1.07–3.71, P < .05, I2 = 72.84%)." (PMID 38394507, 2024). "Several susceptibility loci for alopecia areata were identified: CTLA-4, IL-2, IL-2RA, HLA, ULBP, and Eos." (PMID 29928283, 2018). "A recent genome-wide association study for alopecia areata (AA, OMIM #104000) in humans has implicated several genes, including IL-2RA (for interleukin 2 receptor, alpha chain) in the development of disfiguring hair loss." (PMID 23659281, 2013). "This systematic review and meta-analysis were done to find the association between rs3118470, rs2275913, rs3212227, and rs10889677 of the IL2RA, IL17A, IL12B, and IL23R genes, respectively, of the interleukin family with alopecia areata." (PMID 38394507, 2024). "Throughout the assessment, 165 articles were not related to Alopecia Areata and IL2RA, IL17A, IL12B IL23R genes, 11 were non-English publications and 5 articles were on animal models." (PMID 38394507, 2024). "Alopecia areata lesions also exhibit upregulated expression of genes, such as CCL19, IL-2, IL-15/IL-15RA, IL-2RA/IL-2RB, and Janus kinase 3 (JAK3) responsible for T cell migration and activation compared to regions with normal hair growth in alopecia areata patients." (PMID 29928283, 2018).
cutaneous T-cell lymphoma (6 papers, 2016 to 2023). "Ontak® was approved for the treatment of CD25 positive cutaneous T-cell lymphoma expressing IL-2 receptor alpha (IL2RA)." (PMID 31108917, 2019).
juvenile idiopathic arthritis (6 papers, 2009 to 2024). Juvenile idiopathic arthritis (JIA) is the term used to describe a group of inflammatory articular disorders of unknown cause that begin before the age of 16 and last over 6 weeks. "The aim of this study was to determine whether SNPs within the IL2RA/CD25 gene are associated with juvenile idiopathic arthritis (JIA)." (PMID 19116909, 2009). "stated in an earlier study that IL-2RA was juvenile idiopathic arthritis sensitive gene locus, which may reveal another important pathogenesis of osteonecrosis." (PMID 38745949, 2024).
pneumonia (6 papers, 2020 to 2025). An acute, acute and chronic, or chronic inflammation focally or diffusely affecting the lung parenchyma, caused by an infection in one or both of the lungs (by bacteria, viruses, fungi, or mycoplasma.). "Elevated concentrations of both pro- and anti-inflammatory plasma cytokines were observed in the pneumonia group, including G-CSF, HGF, IL-1b, IL-1RA, IL-2, IL-2Ra, IL-6, IL-10, IL-18, IP-10, monocyte chemoattractant protein-3 (MCP-3), and TNF-α." (PMID 36119044, 2022).
breast carcinoma (5 papers, 2014 to 2023). "IL2RA has also been associated with an increase in breast cancer risk, specifically postmenopausal, as well as mortality." (PMID 37428809, 2023). "The up-regulation of the interleukin-2 (IL-2) and its receptor alpha (IL2RA) are associated with the malignancy of the infiltrating human breast cancer." (PMID 25077705, 2014). "Furthermore, IL15RA and IL2RA are predicted to be targeted by several breast-cancer associated SNPs in cd19 and cd4 primary cells, as well as in vHMEC." (PMID 37428809, 2023). "In contrast, we identified that fractalkine and IL-2RA were higher in metastatic HR+ breast cancer patients who did not experience irAEs, which underscores the importance of investigating disease-specific ICI-related toxicity." (PMID 34548479, 2021).
eczema (5 papers, 2019 to 2025). "Some of the underlying genes, such as FLG, IL6R, CARD11, and IL2RA, were also reported in GWAS on eczema, others were located in or near eczema susceptibility loci." (PMID 38835414, 2023). "Interestingly at all 5 loci, allele frequencies of the risk alleles were significantly higher (FLG, IL2RA) or lower (L1RL2/IL18R1, WDR36/CAMK4, GSDMB) in eczema, distinguishing this allergic disorder of the skin from the allergic airways diseases asthma and hay fever." (PMID 38835414, 2023).
Graves disease (5 papers, 2013 to 2023). Graves' disease is an autoimmune disorder that leads to overactivity of the thyroid gland (hyperthyroidism).It is caused by an abnormal immune system response that causes the thyroid gland to produce too much thyroid hormones. "Genotype and allele frequencies for IL-2RA gene polymorphism (rs7093069) in groups with Graves’ disease (GD) and with Hashimoto’s thyroiditis (HT) compared to control group." (PMID 33193078, 2020). "Among these, PTPN22, CTLA4, HLA_DRB1, FCRL3, and IL2RA are common susceptibility genes between both conditions, while CD40 is exclusively associated with Graves’ disease and RA." (PMID 38093966, 2023). "PTPN22, IL-2RA/CD25, CD40, and SCGB3A2 genes were shown to be associated with Graves’ disease (GD) using candidate gene studies." (PMID 31066758, 2019). "The aim of the study was to analyze the polymorphisms of the IL-2RA (rs7093069), FAIM2 (rs7138803) and PADI4 (rs1748033) genes and their correlation to thyroid hormones and anti-thyroid antibodies in pediatric patients with Graves’ disease and Hashimoto’s thyroiditis compared to the control group." (PMID 33193078, 2020).
hypothyroidism (5 papers, 2023 to 2024). Abnormally low levels of thyroid hormone. "A comprehensive approach integrating PLACO, Bayesian colocalization analysis, MTAG, and TWAS, we successfully identified TYK2, IL2RA, and IRF5 as shared risk genes for both hypothyroidism and RA." (PMID 38332917, 2023). "A common genetic etiology was proposed between hypothyroidism and OLP81 and our study supports this, indicating variation at nine loci (IFIH1, LPP, CEP43, TNRC18, C12orf42, TNFSF11, ST3GAL6, IL2RA, and IKZF3) that are strongly associated with both LP and autoimmune hypothyroidism." (PMID 38776927, 2024). "This comprehensive approach identified TYK2, IL2RA, and IRF5 in hypothyroidism and RA (discovery) utilizing four or three methods." (PMID 38332917, 2023). "TYK2 was consistently identified by all four methods used, while IL2RA and IRF5 were identified in the hypothyroidism and RA (replication) studies using two or three of these methods." (PMID 38332917, 2023). "For instance, patients with FOXP3, IL2RA, and LRBA PNDM may present similar extrapancreatic features (eg, enteropathies, hypothyroidism)." (PMID 38408297, 2024).
influenza (5 papers, 2014 to 2023). An acute viral infection of the respiratory tract, occurring in isolated cases, in epidemics, or in pandemics; it is caused by serologically different strains of viruses (influenzaviruses) designated A, B, and C, has a 3-day incubation period, and usually lasts for 3 to 10 days. "Our transcriptional analysis revealed selective upregulation of the IL-2 receptor alpha chain (Il2ra) by CD69+ CD8+ TRM cells arising in the lungs after influenza infection, potentially indicating increased responsiveness to IL-2." (PMID 30899267, 2019). "Maternal immune activation (e.g., via an infectious exposure such as influenza) has been reported to be associated with risk of SZ and autism, and blood levels of cytokines (e.g., IL1B, IL2RA, IL-6, and TNF) are elevated in SZ patients (see reviews)." (PMID 30115913, 2018).
kidney transplant (5 papers, 2014 to 2025). A surgical procedure in which one or both kidneys from a donor are implanted into a recipient. "In conclusion, IL-2RA induction with early intensified EC-MPS dosing and CNI therapy in de novo kidney transplant patients at low immunological risk may achieve similar three-year efficacy regardless of whether oral steroids are withheld for at least three months." (PMID 24829794, 2014).
Nephropathy (5 papers, 2013 to 2025). A nonspecific term referring to disease or damage of the kidneys. "Some studies have shown that people with certain variants in the IL2RA gene are more likely to develop vascular complications, such as retinopathy, nephropathy, and cardiovascular disease, if they have T1DM." (PMID 38397350, 2024). "In conclusion, hormone-resistant nephropathy was identified by two key genes, IL2RA and KIAA0101, and the signaling pathways involved were the KRAS signaling pathway and the mTORC1 signaling pathway." (PMID 36164371, 2022). "By analyzing the gene sets of different tissues in nephropathy, two key genes, namely KIAA0101 and IL2RA, were obtained." (PMID 36164371, 2022).
celiac disease (4 papers, 2013 to 2024). An autoimmune genetic disorder with an unknown pattern of inheritance that primarily affects the digestive tract. "Forty eight of our DE genes belong to this pathway, including 4 genes that have been genetically linked to coeliac disease: CCR1, IL18RAP, IL21 and IL2RA." (PMID 26444573, 2015). "We found, as in celiac disease, strong upregulation of IL-17 signaling and Th17 cell differentiation in EED including induction of IL21, IL6, IL17A IL17F, IL22, IFNG, IL21R, and IL2RA." (PMID 39300663, 2024).
Cirrhosis (4 papers, 2015 to 2024). A chronic disorder of the liver in which liver tissue becomes scarred and is partially replaced by regenerative nodules and fibrotic tissue resulting in loss of liver function. "Conversely, cirrhosis was linked to decreased levels of IL-2 receptor alpha (IL-2RA), IL-5, IL-7, and tumor necrosis factor beta (TNF-β)." (PMID 39457577, 2024). "Upon detailed assessment, cytokine levels and cirrhosis etiology revealed that HBV-cirrhosis—regardless of antiviral therapy—had a 3-fold increase in IFN-γ, TRAIL and CXCL1 (GRO-α) levels and up to 3-fold decrease in MMP-2, CXCL12, IL2RA, IL-6Rα, CCL2 (MCP1) and CCL21 (6kine) levels." (PMID 36230823, 2022).
enteropathy (4 papers, 2018 to 2024). "IL2RA mutations leads to CD25 protein deficiency and impaired Treg function, resulting in enteropathy, eczema, recurrent viral infections, and autoimmune anemia." (PMID 34122435, 2021).
hyperferritinemia (4 papers, 2022 to 2024). "Our DAG analysis further identified causal associations between IL-18BP, sCD163, M-CSF, IL-8, MIP-1 alpha, and IL-2Ra/sCD25 with increased MCP-1/CCL2, MAS, and hyperferritinemia." (PMID 37674218, 2023).
intermediate uveitis (4 papers, 2013 to 2019). Inflammation of the pars plana. "Another study reported that the variants of IL2RA showed a protective role against the intermediate uveitis." (PMID 31134763, 2019). "We have previously demonstrated an association of intermediate uveitis (IU) with rs2104286, a gene variant of IL2RA." (PMID 26133380, 2015). "Here the role of two IL2RA gene variants (rs11594656 and rs12722495) was investigated in intermediate uveitis and HLAB27 acute anterior uveitis." (PMID 26133380, 2015). "Recently, the IL2RA rs2104286 polymorphism has been associated with intermediate uveitis." (PMID 23676143, 2013). "We for instance have recently found a genetic variant of interleukin 2 receptor alpha (IL2RA) associated with intermediate uveitis (IU), but not with HLAB27 acute anterior uveitis (HLAB27 AAU), suggesting IL2RA as a possible therapeutic target in IU." (PMID 26640809, 2015).
vitiligo (4 papers, 2012 to 2025). Generalized well circumscribed patches of leukoderma that are generally distributed over symmetric body locations and is due to autoimmune destruction of melanocytes. "Recently, a number of genes which play a role in vitiligo susceptibility, including HLA, PTPN22, NALP1, XBP1, FOXP1, IL2RA have been tested for genetic association with vitiligo." (PMID 23284977, 2012). "From a pathophysiology perspective, although the major target cells and antigens are different, MS and vitiligo may have a shared pathologic pathway including increased levels of interferon gamma and IL-17, oxidative stress, and IL2RA gene." (PMID 33082449, 2020). "Here, we identified 13 cell subsets and found that, compared with those in healthy individuals, Treg cells in progressive vitiligo patients are more abundant and express genes such as RTKN2, IKZF2, IL2RA, and STAM." (PMID 41438750, 2025).
allergic disease (3 papers, 2023 to 2024). An immune response that occurs following re-exposure to an innocuous antigen, and that requires the presence of existing antibodies against that antigen. "IP.10 and IL2RA has lower SD compared to the ME, suggesting a more reliable estimated average impact of these two cytokines on allergic reaction." (PMID 39687621, 2024).
atherosclerosis (3 papers, 2022 to 2025). A disease characterized by the build-up of fatty material and calcium deposition in the arterial wall resulting in partial or complete occlusion of the arterial lumen. "IL2RA encodes IL-2 receptor subunit α, which regulates lymphocyte activation and plays an important role in atherosclerosis." (PMID 36299596, 2022).